CCL7 (C-C motif chemokine ligand 7)
Diseases named in the same sentence as CCL7 in open-access papers (continued):
Sharing a sentence is not in itself a finding about the gene and the disease.
Obesity (continued). "Another study examined the CCL7/CCR3 axis in a mouse model of PCa and obesity, specifically in the periprostatic adipose tissue surrounding the tumor, finding that this tissue secretes CCL7, which in turn stimulates the migration of CCR3-expressing tumor cells." (PMID 31500625, 2019). "In our previous study, we reported that 14 adipocyte genes (Ccl7, Emr1, Evi2a, Gusb, H2-DMb2, Lcp1, LOC100041137, Ly9, Ptpre, Rgs1, sc1000528.1_16, Sirpa, Sfrp5, and Acacb) were associated with both advanced age and diet-induced obesity." (PMID 30282902, 2018). "Notably, increased adipose tissue levels of multiple β-chemokines (CCL2, CCL3, CCL5, CCL7, CCL8, CCL11) and chemokine receptors (CCR1, CCR2, CCR3, CCR5) have been linked with obesity and associated metabolic inflammation." (PMID 28396851, 2017). "In obesity, higher secretion of CCL7 by adipocytes facilitates extraprostatic extension." (PMID 26756352, 2016). "This review systematically integrates CCL7's dual roles in tumors (both pro-tumor and anti-tumor) and its stage-specific functions across inflammation (both pro-inflammatory and anti-inflammatory), fibrosis, and obesity, filling gaps in fragmented prior research." (PMID 41630845, 2026). "Adipokines, such as leptin and adiponectin, chemokines, such as CCL7, and metabolites, such as glucose and FFAs, were the targets selected to be quantified as they are key players in prostate tumorigenesis and are differentially secreted by adipocytes in obesity." (PMID 41440554, 2025). "CCL7 may partially mediate the relationship between obesity and DSPN." (PMID 39334887, 2024). "This review provides an in-depth analysis of specific chemokines involved in the development of obesity, including C-C motif chemokine ligand 2 (CCL2), CCL3, CCL5, CCL7, C-X-C motif chemokine ligand 8 (CXCL8), CXCL9, CXCL10, CXCL14, and XCL1 (lymphotactin)." (PMID 39334887, 2024). "In terms of obesity and DSPN, CCL7 is a potential biomarker of inflammation, reflecting its correlation with BMI and waist circumference." (PMID 39334887, 2024). "We have previously demonstrated that adipocytes from PPAT favor the initial step of PPAT infiltration by secreting the CCL7/MCP3 chemokine that attracts CCR3-expressing cancer cells, and this process is amplified in obesity." (PMID 33671469, 2021). "Taken together, our results show that obesity and ageing increased the directed migration of PCa cells by modulating the secretory pattern of adipocytes, this effect being dependent on the CCR3/CCL7 axis." (PMID 33671469, 2021). "In prostate cancer, CCL7, which is secreted by adipocytes, stimulates migration of CCR3-positive tumor cells and acts as a driving force for cancer progression in obesity." (PMID 31963450, 2020). "The secretion, by mature adipocytes of the periprostatic fat, of the chemokine MCP-3/CCL7 supports this process and within the context of obesity this secretion is increased." (PMID 28915700, 2017). "The upregulation of CCL7 secretion in obesity facilitates extraprostatic extension and increases local dissemination, this effect being totally abrogated when the CCR3/CCL7 axis is inhibited." (PMID 26756352, 2016). "Interestingly, CCL7 was only detected in the HFD-fed mice, indicating the potential activation of the CCR5 receptor in obesity conditions only." (PMID 38247865, 2024). "In our lab, we compared both CCR5 and CCL7 expression levels in HME1 cells when exposed (or not) to the obesity micro-environment." (PMID 38247865, 2024). "In the context of obesity and distal sensorimotor polyneuropathy (DSPN), CCL7 serves as a potential inflammatory biomarker, reflecting its correlation with BMI and waist circumference, and appearing to partially mediate the relationship between obesity and DSPN." (PMID 39334887, 2024). "Moreover, depletion of the CCL7/CCR3 axis completely abolishes the ability of obesity to promote tumor metastasis, which reflects the importance of the CCL7/CCR3 axis in prostate cancer in the context of obesity." (PMID 29915688, 2018).
Obesity (continued). "Thus, obesity increases the directed migration of prostate cancer cells by modulating the secretory pattern of mature adipocytes, this effect being mainly dependent on the CCR3/CCL7 axis." (PMID 26756352, 2016).
breast carcinoma (26 papers, 2013 to 2026). "Breast cancer is associated with increased CCL7 expression, while glioblastoma multiforme is accompanied by increased concentrations of CCL2 and CCL7." (PMID 33182504, 2020). "Interestingly, Ccl7 has also been implicated in the pathogenesis of several types of cancer, such as colorectal cancer, breast cancer, and lung cancer." (PMID 39902039, 2024). "In lung fibroblasts, CXCL1, as well as other CXCR2 ligands, increases the expression of CCL2/MCP-1 and CCL7/MCP-3, both of which increase cholesterol synthesis in breast cancer cells in the lung." (PMID 37108425, 2023). "It is seen that the SDG CCL7 is an upstream regulatory gene that promotes early breast cancer survival and invasion through a fibroblast-dependent mechanism in the chemokine signaling pathway." (PMID 37736108, 2023). "Overall, cytokines (excepting CCL7 in the breast cancer and CFB in the prostate cancer system, respectively) are upregulated under both transwell and mixture conditions." (PMID 31963450, 2020). "In the breast cancer model, we found upregulation of the membrane-associated factors, E-selectin, BST2, and HMMR, as well as the cytokine CCL7 only under mixture-culture conditions." (PMID 31963450, 2020). "CCL7 is a ligand for CCR1–3 receptors, among which expression of CCR3 has recently been shown to be associated with luminal-type breast cancers." (PMID 31419632, 2019). "On the one hand, CCL7 itself participates in the recruitment of monocytes and osteoblasts, exerting its pleiotropic tumorigenic roles in breast cancer homing to bone and in metastatic growth." (PMID 29915688, 2018). "Further study showed that CCL7 mainly promotes breast cancer cell proliferation via binding to its receptor CCR1." (PMID 29915688, 2018). "Expression of a critical stem cell gene, Nanog, is increased in response to CCL7 overexpression and promotes the self-renewal of initiating breast carcinoma cells that are transferred to brain tissues." (PMID 29915688, 2018). "Specifically, fibroblast-secreted amphiregulin promoted breast cancer cell survival, whereas the chemokine CCL7 stimulated tumor cell proliferation while CCL2 promoted innate immune cell infiltration and angiogenesis." (PMID 24068959, 2013). "Although CD163+ MØs, CCL2 and CCL7 are associated with cancer metastasis and poor prognosis and high CCL2 levels are found in various cancer types, including breast cancer and some NSCLC31–33, blocking the CCL2/CCR2 axis alone does not impede tumors from recruiting monocyte-origin resident MØs5." (PMID 38076998, 2023). "CCL7 is more elevated in AA women with breast cancer than in CA patients." (PMID 32824813, 2020). "Finally, recent studies confirmed the role of the COX2-MMP1/CCL7 axis in brain cancer metastasis in breast cancer." (PMID 30764543, 2019). "CCL7 secreted by matrix cells is also involved in the bone metastasis of breast cancer cells." (PMID 29915688, 2018). "For this purpose, we investigated CCL7, CCR5, RhoJ, and MMP9 expression in different breast cancer cells: MCF7, MDA-MB-231, MDA-MB-361, ZR751, BT549, and TD47D by using HME1 as a control." (PMID 38247865, 2024). "CCL7, CCL17, CCL20 and CCL25 are significantly more elevated in AA breast cancer patients compared to CA patients." (PMID 32824813, 2020). "Higher expression of CCL7, CCL11 and CCL20 in AA breast cancer patients has been shown to correlate with higher overall survival and better prognoses." (PMID 32824813, 2020). "We found only three small molecules, which concentration differs significantly in both luminal A and luminal B subtypes of breast cancer: IL-13, MCP-1 (CCL2), and MCP-3 (CCL7)." (PMID 31861498, 2019). "In a breast cancer cell and osteoblast co-culture system, MMP-13 stimulates the matrix to produce more CCL7." (PMID 29915688, 2018).
breast carcinoma (continued). "Fibroblasts in breast carcinoma models increase levels of pro-inflammatory chemokines, including CCL2 and CCL7, which enhance infiltration of myeloid immune cells (macrophages, neutrophils) promoting tumor angiogenesis." (PMID 28423685, 2017). "Co-culturing also lead to changes in gene expression in the breast cancer cells, which upregulated a shared receptor for CCL2 and CCL7, the chemokine receptor CCR1 upon co-culturing with tumor-supportive fibroblasts." (PMID 24068959, 2013). "Increased levels of CCL7, CXCL9, and CXCL10 were found in the plasma of breast cancer patients." (PMID 39684443, 2024). "As a tumor suppressor, let-7d specifically binds to the 3’-UTR of CCL7 mRNA and modulates its expression in a negative feedback manner, which is frequently downregulated in many human malignancies, such as lung cancer, breast cancer, and hepatocellular carcinoma." (PMID 33175885, 2020).
atherosclerosis (24 papers, 2012 to 2025). A disease characterized by the build-up of fatty material and calcium deposition in the arterial wall resulting in partial or complete occlusion of the arterial lumen. "On the other side, elafin was also linked to atherosclerosis development alongside other inflammatory markers like E-selectin, Chemokine CC motif ligand 7 (CCL7), IL16." (PMID 40969761, 2025). "A CCL7-deficient animal model may be required to confirm the direct role of CCL7 in the development as well as progression of atherosclerosis." (PMID 36109744, 2022). "These genes are involved in cholesterol metabolism (Abca1, Abcg8, Abcg5, Lpl, Cyp7a1, and Pltp), lipid and atherosclerosis (Abca1, Il1b, Ccl2, and Abcg1), bile secretion (Abcg8, Abcg5, and Cyp7a1), and IL-17 signaling pathway (Ccl7, Il1b, and Ccl2)." (PMID 37301941, 2023). "CCL7 is another candidate that is involved in the formation of ELS in a mouse model of atherosclerosis." (PMID 36717913, 2023). "Altogether, these data seem to indicate that CCL7 is not only a biomarker but also one of the potential contributors to atherosclerosis, especially in the early stages." (PMID 36109744, 2022). "In a mouse model of atherosclerosis, low-density-lipoprotein (LDL)-receptor-deficient mice fed a high-fat diet showed enhanced arterial thrombosis with increased plasma CCL7 expression and altered gut microbial diversity." (PMID 36109744, 2022). "Afterwards, numerous studies have confirmed the crucial role of CCL7 in inflammatory diseases, including infection, atherosclerosis and cancer." (PMID 34189838, 2021). "The rs17735770 genetic variant led to increased expression of CCL7, a potential antagonist of CCR2 at inflammatory sites, where it could play a meaningful role during the evolution of atherosclerosis." (PMID 35711383, 2022). "Some previous studies suggested the potential beneficial effects of CCL7 inhibition by neutralizing antibody or genetic knockout in myocardial infarction, atherosclerosis, aortic aneurysm, acute kidney injury, and in later stages of unilateral ureteral obstruction." (PMID 36109744, 2022). "Cytokine-induced CCL7 expression is enhanced in smooth muscle cells (SMCs) and in the carotid artery after balloon angioplasty, indicating the potential role of CCL7 in the pathogenesis of restenosis and atherosclerosis." (PMID 36109744, 2022). "The role of CCL7 in vascular pathologies, including atherosclerosis, has been reported." (PMID 34830700, 2021). "Increased interaction of various ligand-receptor pairs including Ccl2-Ccr2, Ccl7-Ccr2, and Il1b-Il1r2 between Mesen II and inflammatory cells in ApoE−/− adventitia further implied the participation of Mesen II in early development of atherosclerosis." (PMID 30943771, 2019). "CCL2, CCL7, and CCL12 are major chemoattractants for monocytes and CCL2 deficiency has been reported to result in attenuated accumulation of macrophages in an atherosclerosis model." (PMID 31341173, 2019). "However, inflammatory mediators involved in atherosclerosis development (E-selectin, CCL7, IL16, PI3/elafin) were significantly correlated with AD severity/SCORAD, but not with BMI, strongly suggesting the contribution of cutaneous disease to cardiovascular morbidity." (PMID 28821884, 2017). "The involvement of CCL7‐CCR interaction has been recognized in multiple cardiovascular diseases (eg myocardial infarction and atherosclerosis)." (PMID 34189838, 2021). "In our study, we mainly demonstrated that YB1 dephosphorylation attenuated atherosclerosis in vivo, and YB1 dephosphorylation decreased CCLs (CCL2, CCL7, CCL11, CCL12) expressions in VSMCs in vitro, which may be a critical determinant of the reduction in atherosclerotic plaques." (PMID 35990936, 2022). "Several atherosclerosis mediators in serum (e.g. E-selectin, PI3/elafin, CCL7, IL-16) correlated with SCORAD, but not BMI." (PMID 28821884, 2017).
lung carcinoma (19 papers, 2015 to 2024). "Among the CCR3 ligands, CCL7 has been recently implicated in the dissemination of several cancers such as the dissemination of colon and lung cancers to liver." (PMID 33671469, 2021). "Drugs targeting CCL7 may not only be used in the treatment of lung cancer but also alleviate lung injury caused by different toxins." (PMID 37161570, 2023). "Marked changes in gene expression were measured for Ccl2, Ccl7, Ccl17, Ccl22, Ccl3, Ccl4, Il-1α, Il-1ß, and Il-1rn (inflammation), Lpo and Noxo1 (oxidative stress), and Mmp12 (inflammation/lung cancer)." (PMID 29463257, 2018). "Similarly, CCL7 administration prolonged the survival of mice with lung cancer and enhanced the efficacy of PD-1 ICI." (PMID 39114657, 2024). "This study is consistent with the idea that chemokines may have different roles in different types of cancer and suggests that CCL7 has the potential to be an adjuvant in immune checkpoint therapy for lung cancer." (PMID 39114657, 2024). "This increase in CCL7 in vivo could possibly be due to its increased production by other cell types in the TME, similar to what was shown in a lung cancer model, where loss of CCL7 accelerated tumor growth." (PMID 37733448, 2023). "In addition, it was found that the overexpression of CCL7 in tumor cells could facilitate the anti-PD-1 therapy in lung cancer via recruiting DC1 cells into the tumor immune microenvironment." (PMID 37161570, 2023). "Lung cancer cells express specific chemokines (such as CXCL12/14/16, CCL7/22, CX3CL1, and XCL1) and their corresponding receptors." (PMID 39512767, 2024). "Genes encoding secreted factors, including osteopontin (OPN), chemokine (C-C motif) ligand 7 (CCL7) and thrombospondin 1 (TSP1) were identified, which enhanced tumorigenic properties of lung cancer cells indicative of their potential as targets for therapy." (PMID 26046767, 2015). "Lung cancer CAFs exert their immunosuppressive effects by secreting chemokines, including CCL2, chemokine (C-C motif) ligand 7 (CCL7), chemokine (C-X-C motif) ligand 1, 5, and 8 (CXCL1, CXCL5, CXCL8), and IL-6, which promote the differentiation of CD14+ monocytes into immunosuppressive MDSCs." (PMID 39834587, 2024). "The silencing of CCL7, which was downregulated 2-fold due to PARG’s overexpression, was shown to reduce experimental liver metastasis, whereas CCL5 silencing (downregulated 4-fold in our experiments) reduced metastasis of non-metastatic lung carcinoma cells." (PMID 35585513, 2022).
colorectal cancer (16 papers, 2018 to 2025). A primary or metastatic malignant neoplasm that affects the colon or rectum. "Another study using mice transplanted with colorectal cancer cells (CMT93) transfected with a gene encoding CCL7 also showed tumor growth reduction." (PMID 37046033, 2023). "Indeed, overexpression of Ccl7 was associated with lung adenomas and metastasis in colorectal cancer and renal carcinoma." (PMID 32659965, 2020). "Exosomes from colorectal cancer cell lines affected CCL7 secretion from CAFs, possibly via the miRNA let-7d, and interfered with the migration of CCR2+ monocytic THP-1 cells in vitro." (PMID 33175885, 2020). "In this study, we used a variety of in vitro and in vivo studies in order to discover the role of CCL7 in colorectal cancer progression." (PMID 30764543, 2019). "CCL7 has been reported to be abnormally expressed in the lung and renal carcinoma, and to show pro-proliferative effect in the colorectal cancer cell line HCT116." (PMID 31518371, 2019). "In another study, CCL7 gene transfection to colorectal cancer cell line resulted in tumor growth retardation and metastasis inhibition." (PMID 30764543, 2019). "Even though our study does not provide a strong link between the in situ expression pattern of CCL7 and CCR2, it sets the stage for future studies analyzing CCL7/CCR2 axis in colorectal cancer progression." (PMID 30764543, 2019). "This was the first clinical report presenting CCL7 as a novel target in liver metastasis of colorectal cancer." (PMID 30764543, 2019). "In human liver macrophages, also known as Kupffer cells (KCs), increased CCL7 levels create a favorable microenvironment for colorectal cancer liver metastasis (CRLM)." (PMID 29915688, 2018). "The aim of this study was to determine the role of CCL7 (chemokine (C-C motif) ligand 7) in tumor progression and finding whether it could predict survival of colorectal cancer patients." (PMID 30764543, 2019). "Altogether, we showed that CCL7 is essentially involved in the progression of colorectal cancer in a CT26 mouse model and that the expression of its receptor CCR2 could be related to a different outcome pattern of patients with colorectal carcinoma." (PMID 30764543, 2019). "The pro-tumorigenic properties of CCL7 have also been confirmed in colorectal cancer (CRC) cells." (PMID 29915688, 2018). "However, the mechanisms underlying CCL7 importance in colorectal cancer metastasis have not yet been explained." (PMID 30764543, 2019). "With the progression of tumor, chemokines such as CCL2, CCL7, CCL8, and CCL15 in the microenvironment of colorectal cancer gradually increase, recruiting monocytes and Th1 cells to the tumor region." (PMID 37063892, 2023). "Compared with primary colorectal cancer (CRC), the expression of CCL7 in liver metastases of CRC was significantly increased, suggesting CCL7 as a novel target with potential clinical value in preventing CRC liver metastases." (PMID 35281057, 2022). "Similar to our results, there are reports showing that CCL7 interactions with CCR3 promote the metastasis of neurofibroma and colorectal cancer." (PMID 34206004, 2021). "Altogether, our study identified CCL7 as a factor affecting lung metastasis in CT26 colon cancer model and its receptor, CCR2, as a predictor of the overall survival of colorectal cancer patients." (PMID 30764543, 2019). "Previously, there has not been many studies published analyzing the effect of CCL7 expression on metastasis formation in the colorectal cancer model." (PMID 30764543, 2019). "CCL7, in concordance with our findings, was also reported to be highly expressed in liver metastasis of colorectal cancer when compared to non-metastatic CRC in 30 patients." (PMID 31835892, 2019).